ST6GALNAC1 (ST6 N-acetylgalactosaminide alpha-2,6-sialyltransferase 1)
Diseases named in the same sentence as ST6GALNAC1 in open-access papers (continued):
Sharing a sentence is not in itself a finding about the gene and the disease.
cancer (36 papers, 2012 to 2026). A tumor composed of atypical neoplastic, often pleomorphic cells that invade other tissues. "Lastly, we also tested PODO447 recognition of cancer-associated STn (KI ST6GALNAC1/KO COSMC) and core 3 O-glycans (KI B3GNT3/KO COSMC) and observed no Ab binding to either of these structures." (PMID 35600398, 2022). "ST6GALNAC1 is a key sialyltransferase for the biosynthesis of the cancer-associated Sialyl-Tn (STn) antigen that involved in cell adhesion, invasion, and metastasis in cancers." (PMID 32522293, 2020). "ST6GALNAC1 encodes a sialyltransferase that catalyses the synthesis of the cancer-associated sTn antigen important for cell mobility." (PMID 28382513, 2017). "ST6GALNAC1 encodes the important ST6GalNac1 enzyme that synthesises the cancer-associated sialyl-Tn (sTn) antigen." (PMID 28382513, 2017). "The Tn antigen can be modified by ST6GalNAc1 to produce the truncated cancer-associated sTn antigen, or can be converted to core 1 O-glycan structures." (PMID 27428423, 2016). "ST6GalNAc1 catalyses synthesis of the cancer-associated sialyl-Tn antigen (sTn), which is expressed in a variety of carcinomas and is correlated with metastasis and poor prognosis in patients." (PMID 26452038, 2015). "ST6GalNAc1 encodes a sialytransferase that catalyses formation of the cancer-associated sialyl-Tn antigen (sTn), which we find is also induced by androgen exposure." (PMID 26452038, 2015). "The ST6GalNAc1 enzyme is responsible for the expression of the STn antigen, which is a well-established tumor derived carbohydrate antigen associated to metastasis and poor prognosis of cancer patients." (PMID 32081911, 2020). "The cancer-associated Sialyl-Tn (STn) antigen is a short O-glycan containing a sialic acid residue in an α2,6-linkage to GalNAc α-O-Ser/Thr, and biosynthesis of the STn antigen is mediated by ST6GALNAC1 specifically." (PMID 29348846, 2017). "More specifically, Siglec-15/Sia binding is dependent on Sialyl-Tn (STn), likely synthesised by glycosyltransferases such as ST6GALNAC1, which have shown aberrant expression in cancer." (PMID 39348343, 2024). "ST6GALNAC1’s involvement in STn antigen presentation is frequently upregulated in multiple cancer types and has shown poor prognosis in CRC and prostate cancer (PCa)." (PMID 39348343, 2024). "Although ST6GALNAC1 shares a weak association with TIGIT, the sialyltransferase also shares significant expression with TIGIT, another immune checkpoint associated with cancer progression." (PMID 39348343, 2024). "Our findings reveal a significant positive correlation between ST6GALNAC1, an enzyme implicated in the synthesis of tumor-associated glycans, and MUC1, a mucin glycoprotein frequently dysregulated in cancer." (PMID 38997719, 2024). "Highly expressed in cancer stem cells, ST6GALNAC1 enables cell proliferation, migration, and invasion through upregulated Akt signaling." (PMID 35565748, 2022). "ST6GalNAC1 is one of the candidate enzymes for the Sialyl-Tn synthase, which is strongly expressed in many human carcinomas and is consistent with carcinoma aggressiveness and poor prognosis." (PMID 33936227, 2021). "HST6 cells are MKN45 cancer cells transfected with a vector over-expressing the ST6GalNAc1 glycosyltransferase, which is an enzyme leading to the biosynthesis of the tumor associated STn antigen (Neu5Acα2-6GalNAcα-O-Ser/Thr)." (PMID 32081911, 2020). "Recently, ST6GalNAc-1 has received attention for its ability to control Gal-1- and Gal-3-binding moieties on O-glycans which significantly impact the ferocity of cancer growth and metastasis." (PMID 29423033, 2018). "While several genes were found to be modulated by ST6GALNAC1, we focused our attention on genes with a recognized role in tumor growth and progression, owing the well-known role of sTn in cancer growth." (PMID 28903359, 2017).
cancer (continued). "Although the overexpression of ST6GALNAC1 has been widely studied in different cancer cell models and found to be responsible for increased malignancy, little is known about its role in BC biology." (PMID 28903359, 2017). "Together these data suggest the roles of ST6GalNAc1 will need to be individually analysed in different cancers." (PMID 26452038, 2015). "Although the inhibitory potency is modest, these compounds establish a valuable chemical starting point for targeting cancer-associated sialylation, an effort currently constrained by the lack of structural information for ST6GALNAC1." (PMID 42040468, 2026). "Additionally, another 2,6 siayltransferase, ST6GalNAc1, has been reported to regulate cancer cell adhesion and invasion in prostate cancer." (PMID 39628991, 2024). "The ST6 (alpha-N-acetyl-neuraminyl-2, 3-beta-galactosyl-1, 3)-N-acetylgalacto saminide alpha-2,6-sialyltransferase 1 (ST6GALNAC1) is a member of the sialyltransferase family reported as being overexpressed in several cancers and is correlated with the cancer metastases." (PMID 33936227, 2021). "It remains to be determined whether elevated expression of ST6GALNAC2 may lead to abnormal localization of the enzyme in Golgi apparatus, as described for ST6GALNAC1 overexpressed in cancer cells producing glycoproteins with sialylated GalNAc." (PMID 24398680, 2014). "Key examples of sialyltransferases important in cancer include ST6GAL1; ST3GAL4 ST3GAL6 and ST6GalNAc1/2." (PMID 31614918, 2019). "LINC00261, TNFRSF11A, CASP1, ST6GALNAC1, and PIGR also play prognostic roles in cancer." (PMID 31689990, 2019).
tumor (27 papers, 2014 to 2025). "The putative ligand of Siglec-15, Sialyl-Tn (STn), is associated with tumour progression and is synthesised by the sialyltransferases ST6GALNAC1 and ST6GALNAC2." (PMID 39348343, 2024). "Previous studies have reported that the glycosyltransferase ST6GALNAC1 can promote the synthesis of various tumor-associated MUC1-sialyl-Tn glycans." (PMID 38997719, 2024). "Sialyltransferase ST6GalNAc-1 is highly expressed in tumor cells and associated with tumor aggressiveness and poor prognosis." (PMID 29423033, 2018). "Altered sialylation by enzymes like ST3GAL4 and ST6GALNAC1 can contribute to tumor immune evasion and metastasis and is an emerging therapeutic strategy." (PMID 40018643, 2025). "In conclusion, our research results indicate that sialic acid-related genes, especially ST6GALNAC1, play an important role in immune regulation and tumor progression." (PMID 41445741, 2025). "On the other hand, HBE displayed higher levels of expression of the sialyltransferases ST6GALNAC1 and ST6GALNAC2, which are responsible for biosynthesis of the tumor-associated antigens sialyl-Tn and sialyl-6-T." (PMID 33919332, 2021). "High expression of ST6GalNAc-1 in tumor tissue was an independent prognostic factor for overall survival (p<0.001) and recurrence free survival (p<0.001) in multivariate analysis." (PMID 29423033, 2018). "In malignant cells, α-GalNAc α-2,6-sialyltransferase 1 (ST6GalNAc-1), which adds sialic acid in an α-2,6 linkage to a serine or threonine residue, is responsible for carcinogenesis in types of tumor." (PMID 29423033, 2018). "ST6GALNAC1 was localized on the cellular membrane of tumor cells but also stained the bronchial epithelium." (PMID 27681076, 2016). "Surprisingly, over-expression of ST6GalNAc1-short resulted in a very clear decrease in tumour growth (p< 0.0001, two-way ANOVA)." (PMID 26452038, 2015). "Surprisingly, given its high expression in tumours, stable expression of ST6GalNAc1 in PCa cells reduced formation of stable tumours in mice, reduced cell adhesion and induced a switch towards a more mesenchymal-like cell phenotype in vitro." (PMID 26452038, 2015). "ST6GALNAC1 has been shown to catalyze the addition of sialic acid to glycoproteins and glycolipids, a process that impacts cell signaling, cell adhesion, and immune cell interactions, particularly in tumor tissues." (PMID 41445741, 2025). "Based on the analysis, it was found that the Akt signaling pathway was active in tumor cells with high expression of ST6GALNAC1, and the activation of the Akt signaling pathway could be blocked by knock downing galectin-3 protein." (PMID 30996686, 2019). "Generally speaking, it may be difficult to fully explain ST6GalNAc-1’s pro-tumor effects solely by the regulation of sTn synthesis." (PMID 29423033, 2018). "The researches indicated ST6GalNAc-1 might be involved in tumor development including proliferation, migration, and invasion ability." (PMID 29423033, 2018). "To investigate how expression of ST6GalNAc1 might result in a decrease in tumour mass, we analysed adhesion and mobility properties of the stably transfected DU145 cells." (PMID 26452038, 2015). "It is interesting to speculate that despite ST6GalNAc1 being significantly upregulated in primary prostate tissue where it facilitates cell migration from the primary tumour, a reduction in ST6GalNAc1 may be required to form stable metastases." (PMID 26452038, 2015). "Similarly, overexpression of ST6GalNAc1, thereby sTn epitope, in human breast cancer cells led to increased tumor growth in immunodeficient mice." (PMID 24592356, 2014). "Additionally, GALNT12 and ST6GALNAC1 are associated within the protein-protein interaction (PPI) network, and this interaction may collaboratively regulate the sialylation process, further influencing tumor cell invasion, metastasis, and immune evasion." (PMID 40352586, 2025).
tumor (continued). "Several glycosyltransferases, including MGAT5, FUT8, ST6GAL1, ST6GALNAC1 and ST8SIA1 have an established reputation as tumor-promoting enzymes." (PMID 35565254, 2022). "In experimental models, overexpression of ST6GalNac1 reduced cell-cell aggregation and increased extracellular matrix (ECM) adhesion, migration and invasion in vitro, and promoted tumor growth and metastasis in vivo." (PMID 34975914, 2021). "Using a cut-off of 1.5-fold change, the expression levels of these four genes were down-regulated in CCA tissues compared to non-tumor tissues, evidenced by the percent of tumor cases showing high expression of C1GALT1–29% (26/90), COSMC–7% (6/90), B3GNT6–7% (15/90), and ST6GALNAC1–24% (22/90)." (PMID 35207462, 2022).
infection (3 papers, 2021 to 2024). The state of being infected such as from the introduction of a foreign agent such as serum, vaccine, antigenic substance or organism. "Similarly, at day 7 PI, infection caused a significant decrease of St3Gal4, while St6GalNAc1, St6Gal1, and St3Gal1 showed a trend toward reduction." (PMID 39412866, 2024). "At day 7 PI, expression of St6GalNAc1 increased significantly upon infection, while St3Gal4 expression decreased." (PMID 39412866, 2024). "Another sialyl transferase, ST6GALNAC1, was previously investigated as a drug target against the infection of smooth airways epithelial cells by influenza virus." (PMID 33924631, 2021). "However, expression of all sialyltransferase-encoding genes was mostly downregulated by RVC and both RVA viruses with the exception of ST3Gal4 and the major Sialyl-Tn synthase—ST6GalNAc1 whose expression was marginally upregulated after infection with both RVA strains." (PMID 37848925, 2023).
ST6GALNAC1 also shares sentences with these, for which no sentence is quoted: colorectal cancer (3 papers); Bladder Tumor (2); breast tumors (2); clear cell renal cell carcinoma (2); lung squamous cell carcinoma (2); cardiac hypertrophy (1); colitis (1); essential hypertension (1); gastric tumor (1); glioblastoma (1); melanoma (1); metastatic disease (1); metastatic prostate carcinoma (1); mucinous neoplasm (1); pancreatic cancer (1); Zinc deficiency (1).